UTP4 (UTP4 small subunit processome component)
Description:
Ribosome biogenesis factor. Involved in nucleolar processing of pre-18S ribosomal RNA. Part of the small subunit (SSU) processome, first precursor of the small eukaryotic ribosomal subunit. During the assembly of the SSU processome in the nucleolus, many ribosome biogenesis factors, an RNA chaperone and ribosomal proteins associate with the nascent pre-rRNA and work in concert to generate RNA folding, modifications, rearrangements and cleavage as well as targeted d Involved in SSU pre-rRNA processing at sites A', A0, 1 and 2b. Required for optimal pre-ribosomal RNA transcription by RNA polymerase. May be a transcriptional regulator. (Microbial infection) Acts as a positive regulator of HIVEP1 which specifically binds to the DNA sequence 5'-GGGACTTTCC-3' found in enhancer elements of numerous viral promoters such as those of HIV-1, SV40, or CMV.
Synonyms: CIRH1A; KIAA1988; NAIC; FLJ14728; TEX292; CIRHIN
Tractability: Small molecule: a structure with a bound ligand is known. PROTAC: UniProt records ubiquitination sites on it; ubiquitination databases record sites on it; its protein half-life has been measured.
Gene: Protein-coding gene on chromosome 16 (69,131,291 to 69,231,130, forward strand). Ensembl gene ENSG00000141076.
Subcellular location: Nucleus, nucleolus; Chromosome
Subcellular location (Human Protein Atlas): Nucleoli fibrillar center
Pathways (Reactome):
Metabolism of RNA: Major pathway of rRNA processing in the nucleolus and cytosol; rRNA modification in the nucleus and cytosol
Gene Ontology:
Molecular function: protein binding; RNA binding
Biological process: maturation of SSU-rRNA; regulation of DNA-templated transcription; ribosomal small subunit biogenesis; maturation of SSU-rRNA from tricistronic rRNA transcript (SSU-rRNA, 5.8S rRNA, LSU-rRNA)
Cellular component: chromosome; fibrillar center; nucleolus; small-subunit processome; t-UTP complex; nucleoplasm; 90S preribosome
Genetic constraint (gnomAD): Loss-of-function variants: 41 observed, 69.49 expected, observed/expected ratio (o/e) 0.59, 90% interval 0.46 to 0.77. The upper end of that interval is the gene's LOEUF score, 0.77, which puts it in group 3 of 6, group 1 being the genes least tolerant of losing a copy. Missense variants: 703 observed, 779.21 expected, observed/expected ratio (o/e) 0.9, 90% interval 0.85 to 0.96. Synonymous variants: 300 observed, 276.94 expected, observed/expected ratio (o/e) 1.08, 90% interval 0.99 to 1.19.
Homologues: Orthologues: chimpanzee UTP4 (97% identical), dog UTP4 (95% identical), guinea pig UTP4 (94% identical), rabbit UTP4 (94% identical), pig UTP4 (94% identical), macaque UTP4 (93% identical), rat Utp4 (91% identical), mouse Utp4 (90% identical), zebrafish utp4 (53% identical), Drosophila melanogaster l(3)72Dn (25% identical). Paralogues in human: SKIC8 (11% identical).
Diseases named in the same sentence as UTP4 in open-access papers:
UTP4 is named in the same sentence as 23 diseases in open-access papers, as found by Europe PMC text mining. Sharing a sentence is not in itself a finding about the gene and the disease. The quoted sentences say what the papers report.
Cirrhosis (2 papers, 2017 to 2023). A chronic disorder of the liver in which liver tissue becomes scarred and is partially replaced by regenerative nodules and fibrotic tissue resulting in loss of liver function. "Noteworthy, the disease relevant arginine residue (R565), mutated in the human homolog in patients suffering from NAIC (North American Indian childhood cirrhosis), locates to the Utp4-Utp10 interface." (PMID 28575120, 2017).
biliary cirrhosis (1 paper, 2016). "Mutations in the ribosome biogenesis factor hUTP4 (formerly called Cirhin), cause North American Indian Childhood Cirrhosis (NAIC, OMIM# 604901, UTP4 mutations), a form of biliary cirrhosis." (PMID 27784267, 2016).
glioma (1 paper, 2020). A benign or malignant brain and spinal cord tumor that arises from glial cells (astrocytes, oligodendrocytes, ependymal cells). "In a comparison of low-grade glioma and control, 2 proteins viz., U3 small nucleolar RNA-associated protein 4 homolog (UTP4) and Coiled-Coil domain containing 28A (CCDC28A) showed a significant response." (PMID 33415070, 2020). "Most of the CSF samples procured from GBM patients showed the presence of TA autoantibodies against NOL4 and KALRN while low grade glioma samples showed an antigenic response against UTP4 and CCDC28A." (PMID 33415070, 2020). "Proteins NOL4 (a cancer-testis antigen) and KALRN showed an antigenic response in the CSF of GBM patients, whereas, UTP4 and CCDC28A showed an antigenic response in low grade gliomas when compared with the control samples." (PMID 33415070, 2020).
Indian Childhood Cirrhosis (1 paper, 2013). "North American Indian Childhood Cirrhosis (NAIC) is an autosomal recessive cholestatic disorder caused by missense mutation of CIRH1A, the human homolog of yeast Utp4." (PMID 24147052, 2013).
UTP4 also shares sentences with these, for which no sentence is quoted: cancer (2 papers); tumor (2); adenocarcinoma (1); basal cell carcinoma (1); breast carcinoma (1); cancer of female genital organs (1); cancer of male genital organs (1); cholestasis (1); colon cancers (1); colon tumors (1); Diamond-Blackfan anemia (1); intrahepatic cholestasis (1); Jaundice (1); lymphedema (1); osteosarcoma (1); schizophrenia (1); Shwachman-Diamond syndrome (1); skin cancer (1); Treacher-Collins syndrome (1).